ANO1 (anoctamin 1)
Diseases named in the same sentence as ANO1 in open-access papers (continued):
Sharing a sentence is not in itself a finding about the gene and the disease.
cystic fibrosis (45 papers, 2010 to 2025). Autosomal recessive disorder caused by pathogenic variants in the CFTR gene (cystic fibrosis transmembrane conductance regulator), which encodes a chloride and bicarbonate channel expressed in epithelial cells, and follow the diagnosis criteria. "Mouse Ano1-/-mutants exhibited mucus obstruction and abnormal mucociliary clearance that resemble the airway defects associated with cystic fibrosis." (PMID 32286221, 2020). "Dysfunction of ANO1 is implicated in several disease states including cystic fibrosis, asthma, gastroparesis, hypertension, rota-virus induced diarrhea and polycystic kidney disease." (PMID 25823819, 2015). "Dysfunction of ANO1 is associated with several disease states including cystic fibrosis, asthma, gastroparesis, hypertension, rota-virus induced diarrhea and polycystic kidney disease." (PMID 25823819, 2015). "Recent work has proposed activation or potentiation of Ca2+ activated TMEM16A (anoctamin 1) chloride ion channels as a mutation-agnostic treatment for people with cystic fibrosis and other inflammatory airway diseases." (PMID 34360618, 2021). "Potentiation of ANO1 can provide health benefits for human diseases such as salivary gland dysfunction, cystic fibrosis, dry eye syndrome, and intestinal hypomotility." (PMID 36674697, 2023). "On the other hand, activation of the ANO1 channel was also suggested to have therapeutic potential in human diseases including salivary gland dysfunction, cystic fibrosis, dry eye syndrome, and intestinal hypomotility." (PMID 36674697, 2023). "Here we show that microRNA-9 (miR-9) contributes to cystic fibrosis and downregulates anoctamin 1 by directly targeting its 3′UTR." (PMID 28955034, 2017). "Downregulation of the anoctamin 1 calcium channel in airway epithelial cells contributes to pathology in cystic fibrosis." (PMID 28955034, 2017). "Eact, a synthetic agonist of ANO1, was synthesized for the purpose of treating cystic fibrosis in an attempt to bypass dysfunctioning CFTR channel." (PMID 25231974, 2015). "Because chemical activation of ANO1 is viewed as an alternative means of rescuing cystic fibrosis, understanding its gating mechanism would be useful in developing novel treatments for cystic fibrosis." (PMID 25231974, 2015). "Understanding structural and molecular mechanisms for ANO1 activation is useful in designing anti-cystic fibrosis drugs." (PMID 25231974, 2015). "There are many opportunities for chloride channels in drug discovery, including, for example, increasing ANO1 activity to treat cystic fibrosis." (PMID 20664600, 2010). "An increasing number of studies have revealed that Ano1 expression is upregulated in many diseases, including cancers, hypertension, cystic fibrosis, nonalcoholic fatty liver disease, chronic rhinosinusitis, asthma, diarrhea, gastroparesis, and polycystic kidney disease." (PMID 35610255, 2022). "ANO1 agonists are now considered to be useful in the management of cystic fibrosis." (PMID 25231974, 2015). "In the present study we investigated the effects of the two ANO1-inhibitors niclosamide (Niclo) and benzbromarone (Benz) in vitro and in vivo in mouse models for cystic fibrosis and asthma." (PMID 38233410, 2024). "Anoctamin 1 (ANO1/TMEM16A) was identified as the major Ca2+-activated Cl− channel in airway epithelial cells, and we recently demonstrated that downregulation of the anoctamin 1 channel in cystic fibrosis patients contributes to disease severity via an unknown mechanism." (PMID 28955034, 2017). "In non-cancerous conditions, ANO1 contributes to the pathogenesis of asthma, cystic fibrosis, and hypertension by regulating ion homeostasis and membrane potential, positioning it as a promising therapeutic target." (PMID 40356890, 2025). "Interestingly we also found two cystic fibrosis modifier genes, ANO1 (TMEM16A) and TNFAIP3, downregulated by 60% and 70% respectively, in CNP-exposed cells." (PMID 35995803, 2022).
cystic fibrosis (continued). "Our observations indicate that activators of ANO1, which may be useful in other pathological settings (e.g., compensation for the inactive CFTR chloride channel in cystic fibrosis), could potentially have undesirable effects on tumours through ANO1." (PMID 20664600, 2010). "Expression of the Ca2+ activated Cl− channel (CaCC) TMEM16A (anoctamin 1; ANO1) is upregulated in inflammatory airway diseases such as cystic fibrosis or asthma." (PMID 38233410, 2024).
prostate carcinoma (44 papers, 2013 to 2025). A carcinoma that arises from epithelial cells of the prostate gland. "The goal of this study was to investigate the molecular mechanism underlying ANO1 inhibition in suppression of prostate cancer cell growth." (PMID 29899325, 2018). "In summary, our findings reveal a novel mechanism underlying the role of ANO1 inhibition in suppression of prostate cancer cells and xenograft tumors." (PMID 29899325, 2018). "We previously found that the expression of ANO1 in prostate cancer was upregulated and associated with the progression of cancer malignancy." (PMID 29899325, 2018). "Collectively these evidences support a possible novel mechanism underlying the anticancer effects of luteolin against prostate cancer cells via downregulation of ANO1." (PMID 28362855, 2017). "Additionally and significantly, our studies using in vivo models also provided a new level of insight into the direct association between causative ANO1 expression and resulting phenotypic alterations with respect to prostate cancer bone metastasis." (PMID 38773164, 2024). "In addition, higher expression of ANO1 was significantly associated with advanced phenotypes of prostatic carcinomas and oral squamous cell carcinomas." (PMID 29416639, 2018). "To understand the mechanism underlying the apoptosis induced by ANO1 inhibition, we performed the gene profiling analysis in prostate cancer PC-3 cells and found that ANO1 downregulation caused an increased expression of death receptor signaling molecules, such as TNF-α, TNFSF10 (TRAIL), and CASP7." (PMID 29899325, 2018). "Prostate cancer is the most common type of cancer and the second leading cause of cancer deaths in men, and recent studies suggest ANO1 may be a promising therapeutic target for prostate cancer." (PMID 28362855, 2017). "In addition, the high expression of ANO1 is closely associated with the advanced clinical stages of prostate cancer and ovarian cancer, as well as poor pathological differentiation grades, suggesting that ANO1 expression levels can serve as an important indicator for predicting poor tumor prognosis." (PMID 40356890, 2025). "Moreover, DNA demethylation may be considered as a crucial mechanism to regulate ANO1 expression and function in metastasis-associated transcriptional program in prostate cancer cells." (PMID 38773164, 2024). "Studies have shown that overexpression of ANO1 is closely associated with TNM staging and Gleason scores in prostate cancer, playing a critical role in the proliferation, progression, and metastasis of the disease." (PMID 40356890, 2025). "For instance, Anoctamin 1 (ANO1), a calcium chloride-activated channel involved in cancer proliferation, migration, and invasion, was downregulated by cis-resveratrol in prostate cancer models." (PMID 39942639, 2025). "Silencing or inhibiting endogenous ANO1 has been demonstrated to suppress prostate cancer growth, induce apoptosis, and enhance TNF-α expression." (PMID 40356890, 2025). "TMEM16A, commonly referred to as ANO1, plays a crucial role in the biology of prostate cancer, particularly as a calcium-activated chloride channel (CaCC)." (PMID 40707942, 2025). "In prostate cancer cells, downregulation of ANO1 expression inhibits invasion, migration, and proliferation of cells." (PMID 39830909, 2025). "Collectively, these findings suggest that ANO1 represents a promising anticancer target in prostate cancer therapy." (PMID 40356890, 2025). "For example, luteolin, a natural compound, has been identified as a powerful ANO1 inhibitor, showing significant anticancer properties by reducing ANO1 expression and activity in prostate cancer cells." (PMID 40707942, 2025). "Collectively, our results help elucidate the critical role of ANO1 expression in prostate cancer bone metastases, which is epigenetically modulated by promoter CpG methylation." (PMID 38773164, 2024).
prostate carcinoma (continued). "In contrast, hemin has shown minimal impact on the cell viability of LNCaP (prostate cancer), A549 (lung cancer), and HepG2 (liver cancer) cells, which express negligible levels of ANO1, even at high concentrations." (PMID 38892219, 2024). "Previous studies have indicated that inhibition of ANO1 leads to apoptosis in prostate cancer cells." (PMID 38892219, 2024). "Related to the current report, ANO1 has been proposed to play a role in regulating the proliferation of prostate cancer cells and tumorigenesis in prostate cancer models." (PMID 38773164, 2024). "Our data clearly implicate DNA methylation for ANO1 gene silencing and underscore the importance of this epigenetic process in modulating prostate cancer bone metastasis." (PMID 38773164, 2024). "Here, we evaluated the effect of hemin, which has high clinical applicability, on ANO1 and its anticancer effects on prostate cancer cells." (PMID 38892219, 2024). "To demonstrate the specific impact of ANO1 on prostate cancer cells, we evaluated cell viability in PC-3 ANO1 KO cells transiently subjected to ANO1 transfection." (PMID 38892219, 2024). "Previous studies have shown that inhibition of ANO1 decreases cell proliferation and migration in prostate cancer cells." (PMID 38892219, 2024). "In this study, we conducted a screening to identify novel ANO1 inhibitors with anticancer effects using PC-3 human prostate carcinoma cells." (PMID 38892219, 2024). "In this study, we investigated the expression pattern and oncogenic function of ANO1 using three prostate cancer cell lines with varying degrees of metastatic potential." (PMID 38773164, 2024). "Taken together, these results suggest that hemin, currently used clinically, has a potential to be developed as a new therapeutic agent for prostate cancer overexpressing ANO1." (PMID 38892219, 2024). "Previous studies have endeavored to elucidate the pathophysiological role of ANO1 in prostate cancer." (PMID 38892219, 2024). "These in vitro discoveries were further supported by our in vivo observation that ANO1 expression in xenograft mouse models enhances the metastatic dissemination of prostate cancer cells into tibial bone and the development of osteolytic lesions." (PMID 38773164, 2024). "Anoctamin1 (ANO1), a calcium-activated chloride channel, is overexpressed in a variety of cancer cells, including prostate cancer, and is involved in cancer cell proliferation, migration, and invasion." (PMID 38892219, 2024). "In this regard, ANO1 is a hub promoting metastatic potentials in prostate cancer cells and a promising target for novel therapeutic strategies for bone metastatic prostate cancer." (PMID 38773164, 2024). "ANO1 is often highly amplified and expressed in prostate cancer cells, and is functionally correlated with invasive and metastatic potential of cells." (PMID 38773164, 2024). "Having identified the mechanistic basis for an aberrant expression of ANO1 in prostate cancer cells, we next directed our attention toward understanding its impacts on the metastatic potential of prostate cancer cells." (PMID 38773164, 2024). "Based on these observations, together with findings from previous studies, epigenetic regulation of ANO1 expression can be viewed as a crucial process to modulate prostate cancer-derived bone metastasis." (PMID 38773164, 2024). "ANO1 protein levels in prostate cancer and NSCLC cells were verified and evaluated again after vitekwangin B treatment." (PMID 38659592, 2024). "Since hemin is widely used in clinics for the treatment of porphyria; it has high potential to be developed as a treatment for prostate cancer that overexpresses ANO1." (PMID 38892219, 2024). "Adding support to the idea that ANO1 expression is epigenetically regulated, 5-Aza-CdR treatment generates the hypomethylation of ANO1 CpG islands and the active state of ANO1 gene expression in LNCap/DU145 prostate cancer cells and xenograft models." (PMID 38773164, 2024).
prostate carcinoma (continued). "Both ANO1 inhibitors and downregulation of ANO1 have exhibited anticancer effects against prostate cancer." (PMID 38892219, 2024). "ANO1 inhibitors were applied on prostate cancer cells and significant antiproliferative effects were observed." (PMID 37274097, 2023). "Since ANO1 inhibitors show anticancer effects, cis- and trans-resveratrol were further investigated on their anticancer activities in human prostate cancer PC-3 cells." (PMID 36674697, 2023). "In particular, the anticancer effects of ANO1 inhibition have been well-established in human prostate cancer cells." (PMID 36674697, 2023). "Luteolin not only downregulates the expression of anoctamin 1, a calcium-activated chloride channel, but also inhibit its functional activity that leads to inhibition of cell proliferation, migration and invasion in prostate cancer cells." (PMID 36358791, 2022). "Anoctamin1 (ANO1), a calcium-activated chloride channel, is frequently overexpressed in several cancers, including human prostate cancer and oral squamous cell carcinomas." (PMID 32899792, 2020). "This study revealed that a novel ANO1 inhibitor, Ani-D2, has therapeutic potential for the treatment of several cancers that overexpress ANO1, such as prostate cancer and oral squamous cell carcinoma." (PMID 32899792, 2020). "Previous studies have shown that pharmacological blockade of ANO1 inhibits cell proliferation of metastatic prostate cancer cells and metastasis of oral cancer cells." (PMID 32899792, 2020). "In line with our results, decreased migration and invasion activity with inhibition of ANO1 have been reported in gastric carcinoma, hepatocellular carcinoma, lung cancer, oral squamous cell carcinoma, prostatic carcinoma, colorectal carcinoma, and glioma." (PMID 29416639, 2018). "Our findings show that ANO1 expression in prostate cancer cells is negatively correlated with TNF-α signaling upstream to activation of caspase." (PMID 29899325, 2018). "Taken together, our findings provide mechanistic insight into promoting apoptosis in prostate cancer cells by ANO1 inhibition through upregulation of TNF-α signaling." (PMID 29899325, 2018). "Here, we performed a cell-based screening for the identification of ANO1 inhibitors as potential anticancer therapeutic agents for prostate cancer." (PMID 28362855, 2017). "We further investigated the effects of luteolin on cell proliferation and migration of PC-3 prostate cancer cells expressing high levels of ANO1 endogenously." (PMID 28362855, 2017). "A cell-based screening of natural products was performed to identify novel ANO1 inhibitors as potential anticancer agents against prostate cancer." (PMID 28362855, 2017). "ANO1 is highly expressed in prostate cancer tissues and downregulation of ANO1 results in reduction of proliferation, progression and pathogenesis of metastatic prostate cancer cells." (PMID 28362855, 2017). "In an orthotopic xenograft mouse model of prostate cancer using PC-3 cells, downregulation of ANO1 expression by intratumoral injection of ANO1 shRNA significantly inhibited tumor growth." (PMID 28362855, 2017). "Much higher ANO1 expression was found in human keratinocyte cell line HaCaT, prostate cancer cell line PC-3, and the three colon cancer cell lines SW480, HCT116 and HT-29." (PMID 27732935, 2016). "Knockdown of ANO1 induced apoptosis in prostate cancer PC-3 cells and colon cancer cell lines SW480, HCT116 and HT-29, as compared with cells expressing control shRNA." (PMID 27732935, 2016). "In prostate cancer PC-3 cells, silencing ANO1 reduced the expression of cyclin D1 (CCND1), cyclin A2 (CCNA2), CDK1 and CDK2." (PMID 27732935, 2016). "For instance, inhibition of ANO1 expression in prostate cancer PC-3 cells significantly reduced proliferation, metastasis and invasion, and blocked tumor growth in a xenograft mouse model." (PMID 26196390, 2015).